IL10 (interleukin 10)
Diseases named in the same sentence as IL10 in open-access papers (continued):
Sharing a sentence is not in itself a finding about the gene and the disease.
breast cancer (continued). "The group then moved on to culture MCF-7 breast cancer cells with OSM, IL-10, IL-11, or growth differentiation factor 5 (GDF5) rich serum." (PMID 39123444, 2024). "In contrast, the chronic inflammatory IL signature, including IL-4, IL-5, IL-10, IL-13, IL-17, and CXCL1, showed a significant prognostic effect across the whole cohort of breast cancer patients." (PMID 39456897, 2024). "For example, in the mouse model of breast cancer, TAM represents the main source of IL-10 and inhibition of IL-10 signal transduction can significantly improve the efficacy of chemotherapy." (PMID 38605951, 2024). "Oral atovaquone treatment reduced tumour MDSCs and IL-10 in HCC1806, CI66 and 4T1 paclitaxel-resistant (4T1-PR) breast cancer, leading to a reduction in tumour growth by 45%, 70% and 42% respectively." (PMID 38464388, 2024). "In estrogen receptor-positive breast cancer (ER+ BC, of any stage) patients, we found that ~40% harbor defects in immune signaling at the time of diagnosis, including altered signaling responses to IL-6, IFNγ, TGFβ, IL-10, and IL-4 in various immune cells." (PMID 39389979, 2024). "Secretion of IL-10, which is responsible for the regulation of BCL-2 and STAT3 expressions, induces the activation of the IL-10-STAT3-BCL2 pathway in breast cancer, which enhances drug resistance." (PMID 39309874, 2024). "The EGF produced by TAMs actively stimulates the proliferation of breast carcinoma cells, whereas TAM-produced IL-10 promotes the accumulation of tumor cells at distant sites." (PMID 38533507, 2024). "Lin28B reduced the expression of let-7s in breast cancer exosomes and regulated the expression of CXCL, IL-6, and IL-10 in neutrophils, resulting in immunosuppressive PMN, thus promoting lung metastasis of breast cancer." (PMID 37046819, 2023). "This is supported by the observation of an inverse correlation between IL10 and IL6 levels in breast cancer patients." (PMID 37238004, 2023). "In breast cancer, curcumin can increase M1 and decrease M2 macrophages, resulting in a decrease in STAT3, IL-10, and arginase I gene expression and secretion in mice with metastatic breast cancer." (PMID 37238871, 2023). "Based on in previous study of our group, we showed that PD-L1 protein has a strong immunosuppressive effect under TME by down-regulating IL-10 and TGF-β via M2-TAM in breast cancer." (PMID 36857852, 2023). "IL-10 and STAT3 are involved in the occurrence and development of several diseases, such as AD, breast cancer, glioma, and autosomal dominant hereditary high lgE syndrome." (PMID 35572136, 2022). "After being cultured with breast cancer MDA-MB-453 cell-conditioned medium, macrophages were inclined to the M2 phenotype (IL-10 high, TGF-β high, CD163 high, CCL-17 high, CCL-22 high) in the circWWC3-transfected group as compared to the control group." (PMID 35996149, 2022). "Our previous work with breast cancer patients demonstrated that high levels of TGF-β, TNF-α, VEGF, IL-6, IL-8, and IL-10 correlated with poor prognosis, while IL-21 and CCL-2 are related to a better outcome." (PMID 36428939, 2022). "The breast cancer cell line triple-negative MDA-MB-231 exposed to hBM-MSC-cm overexpresses genes TGF-β, IDO, and IL-10." (PMID 36661506, 2022). "The breast cancer MDA-MB-231 cell line elicits the production of proinflammatory cytokines TNF-α, IL-1beta, IL-6, IL-8, and IL-10." (PMID 36501201, 2022). "A trial of HIFU in breast cancer patients demonstrated a significant decrease in immunosuppressive cytokine levels of TGF-B1, IL-6, and IL-10 after HIFU treatment." (PMID 36612192, 2022). "Several genes, such as IDO1, IL10 and CSF2, have been noticed to have positive correlation with HIST1H1B, and we chose CSF2 that plays critical roles in breast cancer aggressiveness to further analyze its links with HIST1H1B." (PMID 34746019, 2021).
breast cancer (continued). "Apart from this, STAT3 inhibition can regulate the production of various immunomodulator factors in TME of breast cancer, such as upregulation of INFs, GM-CSF and IL-2, downregulation of TGF-b, IL-6, and IL-10 proteins." (PMID 33957948, 2021). "In that study, IL-10 secretion from macrophages induced tumor progression through CD8+ T cell suppression, pointing towards an opposite role of IL-10 in breast cancer progression." (PMID 34944905, 2021). "Breast cancer, for example, is characterized by an elevated secretion of proinflammatory cytokines (IL-1, TNF-α, IL-6) or anti-inflammatory cytokines (IL-10), chemokines and chemokine receptors (CXCL8, CXCR4), and angiogenic factors (VEGF)." (PMID 35111484, 2021). "Our results indicate that the levels of both IL-10 and IFN-γ decreased during interplay between MOs and breast cancer cells." (PMID 33108409, 2020). "In previously reported animal models of breast cancer, TAM-derived IL-10 suppressed CD8+T-cell activation and IL-12 secretion from dendritic cells inhibited CD8+T-cell responses by dendritic cells." (PMID 32726950, 2020). "In our cohort involving 265 breast cancer patients, MTDH and IL-10 expression significantly correlated with clinically characteristic ER and PR status." (PMID 33003428, 2020). "MDSCs in breast cancer show increased secretion of TGF-β, VEGF, and IL-10, which induces EMT and metastasis." (PMID 32726950, 2020). "Except with IL-10, treatment with MET has shown marked differences between its action when MOs are cultured alone and when co-cultured with breast cancer cells." (PMID 33108409, 2020). "Several growth factor–related breast cancer genes (EGF, IGF1, IGF1R, IGF2, IGFBP3, IL10, TGFB1, and VEGF), including 26 SNPs, were used as simulation data to evaluate existing algorithms and the proposed HTGA." (PMID 32554381, 2020). "Evidence indicates that AdSCs release IL-4, IL-8, IL-10, matrix metalloproteinase (MMP)-2, VEGF and SDF-1, which potentiate breast cancer growth and progression." (PMID 28750689, 2017). "In summary, we demonstrate that metastatic breast cancer patients have an increased frequency of circulating KIT+CD11b+ cells, M2-polarized CD11b+ cells and elevated levels of the M2 cytokine IL-10 and CCL20." (PMID 26840567, 2016). "TAMs are the dominant source of IL-10 in mammary carcinomas, and recent work demonstrates that TAM-derived IL-10 blocks CD8+ T cell-dependent responses to chemotherapy by suppression of IL-12 expression by intra-tumoral dendritic cells." (PMID 26918785, 2016). "Liang found that IL-10–592 AA and IL-10–819 TT genotypes significantly increased the incidence of DILI in breast cancer patients." (PMID 25789467, 2015). "In the MDA-MB-231 and IL-10 groups, an additional 20% of MDA-MB-231 breast cancer cell-conditioned medium and 10 ng/ml IL-10 was added." (PMID 25013476, 2014). "In MMTV/neu-transgenic mice, a model of human HER2+ breast cancer, topical treatment with TLR7 agonist imiquimod induced IL-10, and the major source of IL-10 was Tr1 cells." (PMID 24624132, 2014). "It has been revealed that the homozygous IL-10-592AA genotype, indicating homozygosity for the [ATA] haplotype, was protective against breast cancer." (PMID 23460834, 2013). "While not yet a direct target of therapy, IL-10 highlights the importance of counteracting immunosuppression in breast cancer, a theme central to current research in immunotherapy." (PMID 41007766, 2025). "One drug, pegylated IL-10, was tested in clinical trials to boost T cell responses in solid tumors, but results were mixed, and it is not used in breast cancer." (PMID 41007766, 2025). "IL-10, known for its immunosuppressive functions, is not currently the focus of direct targeted therapy in breast cancer." (PMID 41007766, 2025).
breast cancer (continued). "In breast cancer TME, TAMs predominantly assume the M2 phenotype, contributing to cancer cell survival and dissemination through the secretion of cytokines (namely, interleukin (IL)-10, transforming growth factor (TGF)-β, and CCL18." (PMID 40136347, 2025). "Treatment of breast cancer cells with TNF-α alone stimulated the release of IL-1B and IL-10." (PMID 39334821, 2024). "In contrast, IL-10 treatment has surprisingly demonstrated antitumor efficacy, as shown with PEGylated IL-10, which induced the expression of IFNγ and granzymes in the tumor and induced the CD8+ T cell-mediated rejection of breast cancer models in mice." (PMID 39204319, 2024). "In addition, medium produced in vitro by the EPS of human muscle cells and a combination of recombinant myokines CXCL1, IL10, and CCL4 also reduced the growth rate and induced cell death of breast cancer cells." (PMID 39518934, 2024). "Molecular pathways involved in breast cancer but not in lung cancer development are androgen receptor signaling, DNA methylation, estrogen metabolism and signaling, and interleukin-10 (IL-10) anti-inflammatory signaling." (PMID 38982523, 2024). "Monocytes, as a type of inflammatory cells, not only secrete inflammatory factors such as IL-1, IL-6, IL-10, and TNF-α to promote tumor microangiogenesis, but also assist in the adhesion of tumor cells to endothelial cells, thereby promoting breast cancer metastasis." (PMID 38834662, 2024). "IC50 concentrations were given to breast cancer co-culture models (MCF-7/THP-1 and MDA-MB-231/THP-1) planted and merged according to the procedure, and after 24 h using flow cytometry, IL-1β, IL-6 levels of IL-8, IL-10, and TNF-α were measured." (PMID 39175950, 2024). "This could explain the high IL-10 and TGF-β expression detected in the poor prognosis basal-like breast cancer biopsies compared to the luminal and healthy breast biopsies." (PMID 37340387, 2023). "Regular exercise in breast cancer survivors after primary treatment has consistently shown to decrease pro-inflammatory cytokines (IL-2, IL-6, IL-8, TNF-α) and increase anti-inflammatory cytokines (IL-10)." (PMID 37507961, 2023). "In addition, IL-23p19 directly or indirectly promotes the infiltration of myeloid cells such as M2 macrophages and neutrophils, leading to the increased secretion of TGF-β, IL-10, and VEGF, and thus promoting angiogenesis in breast cancer." (PMID 36980564, 2023). "In breast cancer, THP-1 treated with CM from MCF-7 or MDA-MB 231 cells results in the differentiation of THP-1 cells toward macrophages and increases the mRNA expression of M2-type macrophage markers, including CD163 and IL-10." (PMID 35960749, 2022). "Furthermore, interleukin 10 and interleukin two synergistically function to promote cytotoxicity of CD8+ T-cell, which is inhibited by regulatory T cells in breast cancer." (PMID 36035177, 2022). "Exercise reduces the postoperative levels of IGF-1, IL-6, CRP, IL-10 and TNF-α among patients with breast cancer, which may have a significant impact on inhibiting breast cancer recurrence and improving its prognosis." (PMID 36482346, 2022). "Although the effect of PoPEx was not investigated in the context of immunosuppressive and antitumor effects of IL-10 and TGF-β, it has been shown that ellagic acid inhibited the growth of breast cancer cell lines via the TGF-β/Smads pathway or inhibited inflammation by increasing IL-10 production." (PMID 35745713, 2022). "They observed that LCN2 secreted from macrophages in response to IL-10 induces cellular growth and proliferation of MCF-7 breast cancer cells, suggesting that macrophage-derived LCN2s might contribute to tumor development and progression." (PMID 35470375, 2022). "For this reason, in a female mammary tumor model, we studied whether BPA treatment could affect the intratumoral expression of IL-1β, IL-4, IL-6, IL-10, TNF-α, IFN-γ, and VEGF by confocal microscopy immunofluorescence." (PMID 35269666, 2022).
breast cancer (continued). "Higher levels of serum IL-10 have also been reported in breast cancer patients as compared to controls, but we did not detect any association in this work, for all cancers, nor by receptor expression, or by tumor size." (PMID 35948877, 2022). "In addition, elevated serum concentrations of IL-6, IL-10, IL-1β, and TNF-α are found in a variety of cancer types, including breast cancer." (PMID 36482346, 2022). "Therefore, this meta-analysis will focus on the effects of exercise on IL-6, IL-10, IL-1β, CRP, TNF-α, IGF-1 and IGFBP-3 levels in breast cancer patients." (PMID 36482346, 2022). "In addition, using a mouse model of breast cancer, our data showed that HPSE upregulated IL-10 expression and promoted macrophage M2 polarization and T cell exhaustion." (PMID 34461608, 2021). "We observed a positive correlation between IL10 and CCL16 immunostaining in breast cancer tissues." (PMID 33500726, 2021). "Variations of therapeutic KDs might provide benefits for breast cancer by decreasing tumor necrosis factor alpha (TNF-α) and insulin while increasing interleukin 10 (IL-10) and may be a promising adjuvant therapy for various cancers (117, –, 121)." (PMID 33849977, 2021). "We next studied IL10 and CCL16 expressions using immunohistochemistry in breast cancer tissues." (PMID 33500726, 2021). "MTDH and IL-10 protein expression of breast cancer patients usually harbored negative estrogen receptor (ER) or progesterone receptor (PR) status, and late-stage tumors have higher IL-10 expression." (PMID 33003428, 2020). "However, IL1A, IL6, IL10, and NFĸB gene expression in CAF was increased, whereas MMP11 was decreased after co-culture with PBMC from breast cancer patients." (PMID 33396463, 2020). "Gene expression of MMP1 and MMP11 in PBMC from breast cancer patients (n = 54) and control (n = 28); expression of IL1A, IL6, IL17, IFNβ, and NFĸB in breast cancer cell lines (MCF-7 and MDA-MB-231); and, additionally, IL10 and MMP11 in CAF and NF were analyzed by qRT-PCR before and after co-culture." (PMID 33396463, 2020). "With regard to MTDH and IL-10 protein expression status for using univariate and multivariate analysis, the results showed that the protein expression of MTDH and IL-10 in ER-negative or PR-negative breast cancer patients have the worse prognosis." (PMID 33003428, 2020). "Moreover, CD200fc, which mimics the effect of CD200, significantly decreased tumor growth and metastasis in a mouse model of breast cancer, increased IFN-γ and decreased IL-6 expression, and time-dependently altered IL-10 and IL-17 levels." (PMID 32635224, 2020). "TAM-derived IL-10 display increased expression of bcl-2 and STAT3 genes, and the subsequent IL-10/STAT3/Bcl-2 signaling pathway induced TAM-mediated treatment resistance on co-culturing human breast cancer cell lines (T47D, BT549) and TAMs (THP-1)." (PMID 32726950, 2020). "Besides, western blot and immunohistochemistry assays indicated that RLT-03 significantly inhibited the expression of VEGF, EGF, CD34, IL-10, and TGF-β related to the angiogenesis and inflammatory regulation of breast cancer." (PMID 32595723, 2020). "While IL-10 stimulates immunosuppressive FOXP3 expressing T regulatory (Treg) cells, its role in breast cancer remains unclear, as it has been reported to both promote and inhibit breast cancer growth." (PMID 30640711, 2019). "Treating rats with both TAM and JEKHT did not affect Ifn-γ or Il-10 mRNA expression in mammary tumors." (PMID 30640711, 2019). "However, our results for let-7-5p are in agreement with those observed for let7, let-7a, and let-7d that down-regulate IL-6 and IL-10 directly or TNF, IL-6, and IL-1β indirectly in MCF10A, fibroblasts, and breast cancer cells." (PMID 31694049, 2019). "Interestingly, breast cancer-bearing mice treated with a combination of NDV and tamoxifen showed a reduction in IL-10." (PMID 30947706, 2019).
breast cancer (continued). "Moreover, toxicity against breast cancer cells strongly correlated with cytokine inhibition with p = 0.023 for IL-1β and p < 0.001 for TNF-α, IL-6, IL-8, and IL-10." (PMID 31581678, 2019). "In breast cancer, circulating levels of IL-10+ and TGF-β+ NK cells are increased, which inhibits the production of the NK cell effectors, IFN-γ and CD107a, and promotes the migration and invasion of breast-cancer cells." (PMID 29439673, 2018). "Multiple studies have established an immune-modulatory role for miR-146b, including suppression of IL-6 allowing p16-dependent tumorigenesis in breast cancer, as well as suppression of multiple other pro-inflammatory cytokines and chemokines such as TNF-alpha, IL-8, and IL-10." (PMID 30018734, 2018). "Moreover, inflammatory cytokines, such as interleukin (IL)-6, induce LCN2 expression depending on activation of the STAT3 signaling pathway, IL-1β and the tumor cell-derived factor IL-10 also promote LCN2 expression in lung and breast cancer." (PMID 27912767, 2016). "However, the expression and function of ILT4 in breast cancer and the relationship between ILT4 and IL-10 expression in cancer cells are poorly understood." (PMID 24762057, 2014). "We hope our findings may be the preliminary experiment for further study on IL-10 and ILT4 function in human breast cancer." (PMID 24762057, 2014). "Moreover, in the haplotype analysis of IL-10 gene, we also found that patients carrying ATA haplotype were in higher LN involvement (p = 0.022) and higher tumor stage(p = 0.028) of breast cancer at the time of diagnosis compared with others." (PMID 20553628, 2010). "Furthermore, in the haplotype analysis of IL-10 gene, we found that patients carrying ATA haplotype were in higher LN involvement (p = 0.022) and higher tumor stage(p = 0.028) of breast cancer at the time of diagnosis compared with others." (PMID 20553628, 2010). "The findings suggest that the IL-10 ATA haplotype and -1082AA genotype might be adverse prognostic factors in breast cancer in Chinese Han women." (PMID 20553628, 2010). "IL-10, was not produced by PBDCs from healthy donors in contrast to PBDCs from patients with operable breast cancer." (PMID 18588665, 2008). "Interleukin 10 has been shown to exert an inhibitory role over T-lymphocyte reactions and as such has been suggested as a potential inhibitory molecule affecting tumour infiltrating lymphocytes (TIL) in the breast cancer microenvironment." (PMID 11870535, 2002). "Furthermore, TRAF3-expressing breast cancer cells displayed reduced levels of PD-L1 and when co-cultured with PBMCs induced a pro-inflammatory profile with increased CD16-NK cells and higher levels of IFN-γ and TNF-α and lower IL-10 and Tregs in the culture." (PMID 42196397, 2026). "Moreover, the abundant presence of TAMs in basal-like breast cancer could explain the high expression of TGF-β and IL-10 detected in basal biopsies compared to luminal ones." (PMID 37340387, 2023). "A study of 105 breast cancer patients showed that IL-10 expression was higher in patients with higher ER negative and SBR classification; higher serum IL-6 levels were more common in triple negative breast cancer (TNBC) patients and used to monitor predictive therapeutic response." (PMID 36693957, 2023). "In a mouse model of TN breast cancer, treatment with AC and ICRP reduced tumor volume, prolonged survival, increased the numbers of infiltrating and systemic CD8+ T cells, and decreased the numbers of tumor suppressor molecules such as galectin-3, PD-L1, and IL-10." (PMID 34638242, 2021). "This increase may be caused by a rapid growth of mammary tumors in JEKHT only treated rats, rather than be a direct effect of JEKHT on IL-10." (PMID 30640711, 2019). "Interestingly, only the non-metastatic triple-negative MDA-MB-468 breast cancer cell conditioned media had a negative effect on both IL10 and TNFα expression in monocytes." (PMID 31105883, 2019).